IL2 (interleukin 2)
Diseases named in the same sentence as IL2 in open-access papers (continued):
Sharing a sentence is not in itself a finding about the gene and the disease.
co-infection (44 papers, 2010 to 2026). "Similarly, Strongyloides co-infection was associated with decreased frequencies of CD4+ T cells co-expressing TNF-α/IFN-γ or IL-2/IFN-γ/TNF-α at baseline in comparison to individuals with active TB only." (PMID 25211342, 2014). "We found that HIV co-infection in LTB-infected individuals caused a significantly lowered production of PPD-induced Th1 (IFN-gamma and IL-2) cytokines by PBMCs and the systemic pro-inflammatory (TNF-alpha and IL-6) cytokines in plasma." (PMID 39514524, 2024). "Our findings suggested that HIV co-infection in LTB-positive individuals is associated with the diminished production of PPD-induced Th1 (IFN-gamma and IL-2) cytokines by PBMCs and in the plasma level of IL-2 and proinflammatory cytokines (IL-6 and TNF-alpha)." (PMID 39514524, 2024). "In contrast, co-infection induced exclusively H3N2-specific single-cytokine producers CD4+ T cells (85% of IL-2, 8.8% of TNF, and 4% of IFN-γ)." (PMID 37287962, 2023). "The reduced concentration of IL-2 in patients with HIV/TB co-infection was also demonstrated by a number of other researchers." (PMID 34835417, 2021). "In contrast, the HBV/HIV coinfection group has a different unique profile with GM-CSF-IL-4- IL-2-IFN-γ-IL12p70; and IL-7-IL-10 -IL1-β grouping together." (PMID 30815625, 2019). "This is indicated by both the loss of CD4+ IFN-γ and IL-2 secreting cells and the increased frequency of PD-1 expression, which we observed in TB and HIV co-infection." (PMID 26756579, 2016). "IL-2 treatment has been more successfully used for treatment of persistent co-infections with drug-resistant mycobacteria in HIV+ individuals." (PMID 27391012, 2016). "HIV-TB co-infection was consistently and independently associated with a reduced frequency of CD4+ IFN-γ and IL-2-dual secreting T-cells and the proportion correlated inversely with HIV viral load (VL)." (PMID 26756579, 2016). "In summary, HIV co-infection with MTB was associated with a decrease in the amount of cytokine (IFN-γ, TNF-α and IL-2) secreted for HIV-specific CD4+ T cells." (PMID 25781898, 2015). "Of note, in the HIV-infected group, the IL-2 level was higher in the case of co-infection with Cryptosporidium spp." (PMID 23971713, 2013). "The expression of IL-12p70 in the macrophages in the presence of IL-2 was restored by co-infection of mice with recombinant HSV-IL-12p70 virus, which also prevented demyelination." (PMID 21364747, 2011). "Excluding co-infection with soil-transmitted helminths, individuals with C. sinensis still had significantly higher antigen-specific IgG and IgE levels, and diminished serum levels of IL-1β, IL-2, IL-4, IL-12p70, IL-17A, IFN-γ and TNF-α." (PMID 36083861, 2022). "Other work has sought to better understand the role of IL-2 in the mechanism of the co-infection." (PMID 33137906, 2020). "Furthermore, our findings suggest only limited potential of IL-2/anti-IL-2 complexes as adjunctive therapy of Mtb/HIV co-infection." (PMID 27391012, 2016). "Furthermore CD4+ PPD-specific cells secreting IFN-γ and IL-2 and expressing CD127 were relatively less frequent in HIV co-infection indicating another potential mechanism of the loss of this key subset." (PMID 26417433, 2015). "In addition, the diminished systemic production of IL-2, IL-17A and IL-17F also indicate a more extensive impairment in Th1 and Th17 responses in co-infection settings." (PMID 25211342, 2014). "Interestingly, the co-infection group showed a higher IL-2/IL-10 and IFN-γ/IL-10 ratios, indicating a more pronounced effort to activate T-cells and macrophages and an overreaction might potentially provoke a collateral damage." (PMID 40014608, 2025). "On the contrary, during HIV and M. tuberculosis co-infection, M. tuberculosis is reported to secrete the EspR protein, a transcription regulator that localizes into the cell nucleus where it binds to the promoter region of the IL-2 gene, resulting in high expression of the IL-2 protein." (PMID 38255719, 2024).
co-infection (continued). "In this present study, we find that the people with IL-2 ≥ 77(pg/ml) were more susceptible to coinfection with HIV and Cryptosporidium spp., which indicate that T lymphocytes are involved in the immune response to the co-infection, although a decrease of IL-2 was observed with the HIV infection." (PMID 22330320, 2012). "We also examined the impact of index case HIV co-infection on Mtb infection as defined by various positivity endpoints using ESAT6/CFP10 responses for TNF, IL-2, and QFT-Plus IFN-γ." (PMID 39606489, 2024). "We hypothesized that ESAT6/CFP10 TNF and IL-2 responses improve Mtb infection detection among exposed household contacts (HHCs) and are associated with index case Mtb aerosolization (i.e., cough aerosol culture positive for Mtb growth, CAC+]) and HIV co-infection." (PMID 39606489, 2024). "Among single cytokine-producing cells, a high proportion of IL-2-expressing CD4+ and CD8+ T cells were found after co-infection." (PMID 37287962, 2023). "After co-infection, CD4+ T cell IL-2 responses also dominated but peaked at 14 dpi (mean of 0.12%) and then declined over time." (PMID 37287962, 2023). "Overall, the results showed upregulation of cytokines IL-10, IFN-γ, and IL-6 and downregulation of IL-12p70, Il-2, and TNF-α during severe Babesia co-infection in mice." (PMID 35719355, 2022). "Overall, these data show that HIV coinfection leads to persistent skewing of CD4/CD8 ratio in the lung and a deficit in lung T cell functionality, most notably in IL-2 and IL-17 production." (PMID 33848273, 2021). "CMV-specific cells expressed PD-1 relatively more frequently in those with HIV co-infection in polyfunctional subsets secreting IFN-γ e.g. IFN-γ and IL-2-dual secreting cells." (PMID 26417433, 2015). "In HIV co-infection CD127 was relatively less frequently expressed on MTB-and CMV-specific IFN-γ and IL-2-dual-secreting cells compared with EBV-specific CD4+ cells than in those without evidence of HIV infection." (PMID 26417433, 2015). "Compared to other pathogens, MTB-specific T-cells were uniquely impacted by HIV co-infection, as there was attenuation of the frequency of the CD4+ IFN-γ and IL-2-dual response." (PMID 26417433, 2015). "The previous studies have shown the correlation between the hereditary susceptibility of gene and liver disease, such as SNPs of aldehyde dehydrogenase 2 (ALDH2) and HCC, interleukin-2 (IL-2), IFN-γ, IL-10 and the infection of HBV, HCV, or HBV/HCV coinfection." (PMID 22690243, 2012). "Additionally, the serum concentration of IL-2 and IL-8 were also significantly increased in the Mtb single infection group, compared to the HIV/Mtb co-infection." (PMID 38799434, 2024). "We assessed the utility of Mtb-specific TNF and IL-2 (from supernatants of the QFT Plus TB1 antigen tube) in improving Mtb infection detection in HHCs of TB participants and the effect of index case aerosolized Mtb and HIV co-infection on cytokine responses." (PMID 39606489, 2024). "In the present study, the levels of IL-2, IL-6 and TNF-α were markedly higher, while the level of IL-10 was markedly lower in HIV/HBV coinfection group than those in HBV infection group and control group, suggesting that HIV worsens HBV-induced inflammatory response." (PMID 38357144, 2023). "High frequencies of PRRSV-2-specific CD8β+ T cells expressing TNF were observed in PRRSV-2 single-infected and PRRSV-2/H3N2 co-infection groups (64.50% vs. 45.05%, respectively), followed by double TNF/IL-2 (6.39% vs. 29.05%, respectively) and TNF/IFN-γ (28.96% vs. 25.63%, respectively) producers." (PMID 37287962, 2023). "These cells were principally derived from the TCM subset irrespective of pathogen specificity and MTB-specific IFN-γ and IL-2-dual secreting CD4+ cells expressed relatively little CD127 in HIV co-infection and very little PD-1 regardless of HIV infection." (PMID 26417433, 2015).
co-infection (continued). "In addition, IFN-γ producing CD8 T cell frequencies were increased in spleens from co-infected mice and frequencies of hepatic IL-2 producing CD4 and CD8 T cells were reduced upon co-infection in comparison to those infected with M. tuberculosis only." (PMID 23110184, 2012). "In HIV/HCV co-infection group, IL-2 concentration was the highest without statistical difference (p > 0.05)." (PMID 22533731, 2012). "In general, the observed impaired production of Th1 cytokines (IFN-gamma and IL-2) and pro-inflammatory cytokines (TNF-alpha and IL-6) during HIV co-infection in LTB-infected individuals might favor intracellular Mtb growth and fail to control the conversion of LTBI into ATB." (PMID 39514524, 2024). "Elevated TGF-β production in PBMCs from patients with HIV/TB co-infection than from healthy controls was also observed, and high level of TGF-β in HIV patients might be a reason for defective MTB-specific IL-1β, IL-2 production and activation of latent TB in HIV." (PMID 37483385, 2023). "HPgV-1 reduced IL-2 and PHA stimulated latent HIV reactivation in vitro, suggesting that HPgV-1 may hinder activation-induced therapeutic “cure” strategies for HIV, especially since up to 41% of PLWH HPgV-1 coinfection." (PMID 35707535, 2022). "However the proportion of the total response to PPD or MTB peptides contributed by CD4+ T-cells secreting IFN-γ and IL-2 together was lowest in active TB/HIV compared with LTBI without HIV co-infection." (PMID 26756579, 2016). "CD4+ MTB-specific T-cells secreting both IFN-γ and IL-2 were reduced in frequency in individuals with HIV-TB co-infection (whether active or latent) unlike other IL-2 secreting subsets." (PMID 26756579, 2016). "Surprisingly, CD4 counts did not increase in those with HPgV-1 co-infection whereas those without HPgV-1 had a rise of more than 1,000 CD4 cells/mm3, suggesting that HPgV-1 interferes with CD4 expansion and IL-2 signaling." (PMID 35707535, 2022). "In conclusion, our study provides evidence that the combination of Th1 cytokines [IFN-γ, TNF-α, IL-2 and IL-12(p70)] have a potential to discriminate between culture-positive and -negative pulmonary tuberculosis with HIV co-infection." (PMID 31086619, 2018). "The frequency of MTB-specific CD4+ tri-functional T-cells secreting IFN-γ, IL-2 and TNF-α was independent of both mycobacterial burden and HIV co-infection." (PMID 26756579, 2016). "However, whether IL-2/anti-IL-2 cytokine complex-mediated cell expansion can be harnessed as an effective measure to boost immunity against active TB, or to prevent TB reactivation after HIV co-infection, is not known." (PMID 27391012, 2016).
vasculitis (44 papers, 2008 to 2025). "In HCV-induced vasculitis patients, “ultra-low” doses of IL-2 induced expansion of CD4+CD25+FOXP3+ Tregs, while effector T-cells appeared relatively unaffected, encouraging the use of IL-2 as a therapeutic strategy in other vasculitides." (PMID 35296082, 2022). "A Phase I/II clinical trial on low dose IL-2 therapy in HCV-induced vasculitis increased Treg levels and reduced vasculitis." (PMID 35069220, 2021). "Patients with HCV vasculitis were treated with IL-2 in a Phase I/II clinical trial with the objective of increasing Tregs, which had been shown previously to correlate with successful treatment of this disease process." (PMID 26834735, 2015). "The IL-2 dose was also three-fold higher than that used in a successful clinical trial of IL-2 to expand Treg in HCV-induced vasculitis." (PMID 24205242, 2013). "PBMCs were isolated from 10 patients with biopsy-proven ANCA+ vasculitis, each paired to a normal control individual, and cultured in the presence of CpG-B and IL-2." (PMID 18625057, 2008). "Similarly to the trials in GVHD, the treatment with IL-2 led to clinical improvement of vasculitis in 8 out of 10 patients." (PMID 25322151, 2014). "This concept has been widely used in clinical practice, and currently, low-dose IL-2 is being used for the treatment of diseases, including graft-versus-host disease (GVHD), TID, hepatitis C virus-induced vasculitis, spinal arthropathy, and SLE." (PMID 33013198, 2020). "The level of IL-2 affects the immune tolerance mediated by Treg cells, while low dose of IL-2 can selectively activate Treg in T1D, HCV-induced vasculitis, GVHD, alopecia areata and SLE." (PMID 31484501, 2019). "Recent studies found that low dose of IL-2 can promote the number of Treg in T1D, HCV-induced vasculitis, GVHD and alopecia areata." (PMID 31484501, 2019). "This clinical study confirmed the correlation of clinical improvement with boosting functional Tregs, and showed that low-dose IL-2 exhibited an intrinsic capacity for Treg recovery, thus improving an autoimmune condition such as HCV-induced vasculitis." (PMID 25322151, 2014). "The current study noted that serum PDGF-CC levels in KD patients were positively correlated with WBC, N%, IL-2, IL-12p70, TNF-α, and IL-1β and negatively correlated with L%, supporting the hypothesis that PDGF-CC exerts its effect in the KD vasculitis." (PMID 38273388, 2024). "More recently, Ld-IL2 was shown to expand TREG cells to improve autoimmune condition in patients with HCV-induced vasculitis, without suppressing anti-viral immunity and increasing HCV viral loads." (PMID 34618873, 2021). "This notion is supported by the observation of a previous clinical trial showing that Ld-IL2 ameliorated hepatitis C virus-induced vasculitis without perturbing virus control." (PMID 34618873, 2021). "Furthermore, treatment with IL-2 in low doses was able to reestablish the Treg cell niche, in addition to clinically improving patients’ clinics with vasculitis induced by the hepatitis C virus (HCV) without any significant adverse effects." (PMID 35740942, 2022). "Another clinical study in patients with vasculitis induced by the hepatitis C virus showed that the administration of low-dose IL-2 increased the percentage of Tregs without adverse effects in all subjects and led to the improvement of vasculitis in most patients." (PMID 34945203, 2021).
metastatic carcinoma (41 papers, 1998 to 2025). A carcinoma which has spread from the original site of growth to another anatomic site. "Reduced levels of IL-2 have been associated with a lower survival of metastatic cancer patients, and numerous trials have been performed using IL-2 alone or in combination with other forms of immunotherapy and chemotherapy." (PMID 19935800, 2009). "The present study was performed to evaluate the impact of a spiritual approach consisting of Kriya Yoga program alone or in association with melatonin (MLT) or low-dose IL-2 plus MLT on the survival time in a group of metastatic cancer patients with life expectancy less than 1 year." (PMID 21654973, 2011). "Based on this important finding, researchers began a clinical trial testing the administration of autologous, activated NK cells in combination with IL-2 in various metastatic cancers." (PMID 38545115, 2024). "Despite the importance of IL-2 against metastatic cancer, this cytokine has various limitations, including its dual action on regulatory T cells (Tregs) and effector T cells." (PMID 38195534, 2024). "The initial indications were in metastatic cancers where IL-2 had to be administered at very high doses (HD IL-2) to achieve clinical benefit." (PMID 37741949, 2023). "The observed anti-tumor effects of IL-2 led to many studies using either a high-dose bolus regimen or a continuous infusion of IL-2 in patients with metastatic cancer." (PMID 37174716, 2023). "In 1985, 25 patients diagnosed with metastatic cancer refractory to standard therapies were treated at the NCI with increasing doses of IL-2, until toxicity precluded dose escalation." (PMID 37174716, 2023). "NK cell proliferation and cytolytic activity can be stimulated by IL-2 at high concentrations which is an essential component of various metastatic cancer therapies." (PMID 33407826, 2021). "As a potent lymphocyte activator, interleukin-2 (IL-2) is an FDA-approved treatment for multiple metastatic cancers." (PMID 33986267, 2021). "The earliest studies from Steve Rosenberg investigated the systemic administration of lymphokine-activated killer cells (patient lymphocytes cultured ex-vivo in the presence of IL-2 then re-infused) and IL-2 in patients with metastatic cancer." (PMID 33923528, 2021). "High dose IL-2 treatment is advantageous in treating metastatic cancer due to heightened activity of natural killer cells toward the tumors." (PMID 33407826, 2021). "Owing to its ability to stimulate effector-type immune cells, high-dose interleukin-2 (IL-2) was the first approved immunotherapy for metastatic cancer." (PMID 33353953, 2020). "This is the firm starting point to employ IL-2 immunocytokine to improve the patients' survival and to treat metastatic cancers as well." (PMID 30619269, 2018). "NK cells, together with CTL, mediate the effect of high dose IL‐2 treatment reported in early clinical trials in patients with metastatic cancers." (PMID 26564811, 2016). "The combination of YM155 and IL-2 induced a significant antitumor effect in orthotopic renal and lung metastatic carcinomas compared with that induced by administration of either agent alone." (PMID 26023798, 2015). "It is known that reversible thyroid dysfunction occurs in up to 60% of metastatic cancer patients treated with immunotherapy consisting of IL-2 alone or in combination with interferon-α or lymphocyte-activated killer cells." (PMID 15026795, 2004). "This study was performed to evaluate the effects of subcutaneous (s.c.)low-dose IL-2 on IL-12 secretion in metastatic cancer patients." (PMID 9667674, 1998). "Interleukin-2 (IL-2) was first identified in 1976 and has since been demonstrated to effectively enhance the production of T lymphocytes in large quantities when administered to individuals with metastatic cancer." (PMID 40075727, 2025).